DNMT1 (DNA methyltransferase 1)
Diseases named in the same sentence as DNMT1 in open-access papers (continued):
Sharing a sentence is not in itself a finding about the gene and the disease.
breast cancer (continued). "We previously showed that, among the three DNA methyltransferases (DNMT1, DNMT3A and DNMT3B), only DNMT3B overexpression is associated with poor outcome in breast cancer." (PMID 15606925, 2004). "Further research into DNMT1 inhibition could contribute to the development of novel therapeutic strategies for this difficult-to-treat breast cancer subtype." (PMID 41602389, 2026). "To further investigate whether DNMT1 promotes breast cancer brain metastasis through RASSF1A methylation, we utilized a CTC-derived breast cancer brain metastasis mouse model." (PMID 41381440, 2025). "Additionally, pSTAT3 has been shown to upregulate DNMT1 expression in various cancers, including hepatocellular carcinoma, lymphoma, colon, and breast cancer." (PMID 40427627, 2025). "To further validate whether DNMT1 promotes the malignant behavior of breast cancer cells through RASSF1A methylation, we silenced RASSF1A in 4T1 cells." (PMID 41381440, 2025). "In conclusion, these findings suggest that DNMT1 may serve as a critical regulator in breast cancer brain metastasis." (PMID 41381440, 2025). "Kaplan–Meier curve analysis showed that neither DNMT1 nor RASSF1 high expression was significantly associated with OS or disease-specific survival in breast cancer patients (log-rank P > 0.05)." (PMID 41381440, 2025). "Notably, recent studies have demonstrated that DNMT1 promotes breast cancer progression, influencing tumorigenesis and stemness." (PMID 41381440, 2025). "If the molecular findings presented here are validated in preclinical models, subsequent clinical trials could evaluate the therapeutic efficacy of DNMT1-targeted interventions in breast cancer." (PMID 41381440, 2025). "For example, in prostate cancer cells DNMT1 was shown to play a tumor-suppressive role while DNMT3B displayed oncogenic function by inducing EMT-associated phenotypes in head and neck squamous cell carcinoma, breast cancer, and ovarian cancer cells." (PMID 40764968, 2025). "In breast cancer, the downregulation of FOXO3a by DNMT1 could promote breast cancer stem cell properties and tumorigenesis." (PMID 39991565, 2025). "Similarly, recent findings revealed that the knockdown of DNMT1 inhibited the progression of breast cancer cells by enhancing the MEG3 expression through demethylation." (PMID 38277283, 2024). "In addition, deletion of DNMT1N in breast cancer cell lines was shown to diminish the histone deacetylase inhibitor LBH589-induced ubiquitylation-dependent degradation of DNMT1 and resulted in genomic hypermethylation." (PMID 38382673, 2024). "The silencing of TSG by DNMT1 promotes breast cancer progression and contributes to metastasis." (PMID 38257347, 2024). "In breast cancer, genistein enhances the ERα expression, and its combination with trichostatin A, a known HDACi, further increases ERα expression by promoting histone acetylation and inhibiting DNMT1 expression." (PMID 39858410, 2024). "The overexpression of piR-651 can promote the proliferation and invasion of breast cancer cells, and its regulatory mechanism is through recruiting DNMT1 to the promoter region of the tumor suppressor gene PTEN through PIWIL2, and the PTEN promoter is methylated, thus reducing its expression level." (PMID 36882835, 2023). "PEITC-treated breast cancer cells displayed the reactivation of CDH1 that could be due to the decreased activity of DNMT1, DNMT3a, DNMT3b, HDAC1, and HDAC2." (PMID 36765652, 2023). "Taken together, we revealed a feedback loop of PAX5 and miR-142, which could affect breast cancer progression by regulating DNMT1 and ZEB1." (PMID 37403081, 2023). "In a previous study, miR-142-5p could directly bind to the 3′-UTR region of DNMT1 in breast cancer cells to promote re-expression of the maspin tumor suppressor gene, resulting in inhibition of the migration and proliferation of tumor cells." (PMID 37631988, 2023).
breast cancer (continued). "DNMT1 is essential for maintenance of DNA methylation, proliferation, survival and facilitates metastasis in breast cancer, where as silencing of DNMT1 inhibits proliferation, migration and invasion abilities of breast cancer cells." (PMID 36774386, 2023). "We validated the findings through CRISPR editing of the DNMT1 gene in MCF7 breast cancer model." (PMID 37045940, 2023). "Although the expressional regulation of its target genes such as DNMT1, DNMT3A and DNMT3B has been reported in breast cancer cells, one of its notable underlying mechanisms for the progression of malignancy is its binding with its target proteins and regulation of their activity." (PMID 38060527, 2023). "Lastly, in vivo experiments showed that knockdown of DNMT1 could suppress breast cancer growth and metastasis." (PMID 35255904, 2022). "DNMT1 is necessary for breast cancer cell migration and invasion." (PMID 36273188, 2022). "This means that depletion of DNMT1 suppresses breast cancer cell metastasis in vivo." (PMID 36273188, 2022). "In addition, MUC1-C induces the expression of DNMT1 and DNMT3b in breast cancer and induces the DNA methylation of CDH1 tumor suppressor gene and the induction of E-cadherin expression." (PMID 35978806, 2022). "In addition, we revealed that TAM-stimulated DNMT1 transcriptional expression via the IL-6-pSTAT3-ZEB1-DNMT1 axis is necessary for TAMs to promote breast cancer metastasis in the tumour microenvironment." (PMID 36273188, 2022). "This means that DNMT1 is required for TAMs to promote breast cancer cell migration." (PMID 36273188, 2022). "Moreover, a prior study uncovered the involvement of DNMT1 in several malignant tumors including breast cancer, while also exhibiting high expression levels in breast cancer." (PMID 35255904, 2022). "We speculated that DNMT1 might also play a critical role in TAM-induced breast cancer cell migration." (PMID 36273188, 2022). "Furthermore, we present clear indication that high levels of DNMT1 in tumor cells as well as their adjacent stromal fibroblasts predict poor survival post-neoadjuvant treatment of locally advanced breast cancer patients." (PMID 35719957, 2022). "Correlations between DNMT1 expression and clinicopathological features in breast cancer patients." (PMID 35719957, 2022). "In addition, we confirmed that there were positive correlations among CD163 (TAM marker) expression, ZEB1 expression and DNMT1 expression in breast cancer patient tissues." (PMID 36273188, 2022). "Next, we explored the functions of DNMT1 in breast cancer tumorigenesis and metastasis in vivo." (PMID 36273188, 2022). "DNMT1 has been shown to be highly expressed in a variety of cancers, including breast cancer." (PMID 36273188, 2022). "Furthermore, RT-qPCR illustrated suppression of miR-497 and elevation of DNMT1 in breast cancer tissues when compared to adjacent normal tissues." (PMID 35255904, 2022). "Therefore, we further examined influence of the interaction of MEG3 with DNMT1 on the breast cancer cells." (PMID 35109842, 2022). "It was found that DNMT1 was notably increased, while miR-497 was poorly-expressed in breast cancer." (PMID 35255904, 2022). "Similarly, physcion 8-O-β-glucopyranoside inhibits breast cancer metastasis by silencing DNMT1, which is line with our findings." (PMID 35255904, 2022). "For instance, the lncRNA TINCR may operate as a competitive endogenous RNA in human breast cancer by recruiting DNMT1 and driving carcinogenesis through the STAT3-TINCR-EGFR signaling axis." (PMID 36157234, 2022). "Therefore, the current study set out to explore how DNA methyltransferase 1 (DNMT1) affects breast cancer through mediating miR-497/GPRC5A axis." (PMID 35255904, 2022). "Taken together, our results indicate that DNMT1 is required for breast cancer cell EMT progression." (PMID 36273188, 2022).
breast cancer (continued). "For instance,piR-651 could promote cell proliferation and migration and inhibit apoptosis in breast cancer by facilitating DNMT1-mediated PTEN promoter methylation." (PMID 36249068, 2022). "SFN may target the aberrant hypermethylation status by downregulating the expression of DNMT1 and DNMT3a in breast cancer cells." (PMID 36235389, 2022). "The roles and functions of DNMT1 in breast cancer have been well reviewed." (PMID 35620052, 2022). "Hypermethylation of WIF1 promoter was observed in 67% of breast cancer cells, which was mainly due to the cooperative activity of DNMT1 and DNMT3b, suggesting that WIF1 epigenetic silencing could link to Wnt dysregulation and breast carcinogenesis." (PMID 35620052, 2022). "DNMT1 is required for TAM-mediated breast cancer cell migration." (PMID 36273188, 2022). "Expression of DNMT1 in cancer cells and stromal fibroblasts by breast cancer ER/Her2 subtypes." (PMID 35719957, 2022). "Furthermore, several studies have shown that the expression of DNMT1 is higher in various types of breast cancers compared with paired normal breast tissues, and that DNMT1 upregulation is associated with higher grades of the disease and poor survival." (PMID 35719957, 2022). "Moreover, our findings advocate DNMT1 as a potential epigenetic drug target to revive the suppressed TSG RUNX3 in breast cancer therapeutics." (PMID 35898303, 2022). "CircRNA DNA methyltransferase 1 (circ-DNMT1), an example of carcinogenic circRNA, increases cell malignant behavior; meanwhile, it has been reported that circ-DNMT1 is involved in the development of breast cancer by promoting cancer cell survival and invasion, as well as inhibiting apoptosis." (PMID 35296654, 2022). "Our study indicates that DNMT1 is necessary for TAM-mediated breast cancer metastasis." (PMID 36273188, 2022). "We next intended to illustrate the detailed mechanism of high DNMT1 expression in breast cancer." (PMID 36273188, 2022). "Inhibiting DNMT1 expression or its activity is a powerful method for breast cancer therapy." (PMID 36273188, 2022). "Our data strongly show that DNMT1 can induce the EMT program in breast cancer cells." (PMID 36273188, 2022). "Here, we first indicated that DNMT1 is required for TAMs to stimulate breast cancer cell migration." (PMID 36273188, 2022). "Likewise, the level of DNMT1 was higher in the group with low expression of PAS1 than in the group with high expression of PAS1, indicating that DNMT1 levels are negatively correlated with PAS1 levels in breast cancer tissues." (PMID 35307730, 2022). "Our study indicates that DNMT1 is critical for TAM-mediated breast cancer metastasis." (PMID 36273188, 2022). "This suggests the need for DNMT1 to promote metastasis and invasion in breast cancer." (PMID 35743249, 2022). "Moreover, we detected DNMT1 functions in breast cancer cell motility by transwell migration assays and Matrigel invasion assays." (PMID 36273188, 2022). "In addition, the same laboratory demonstrated that 5′-Aza-2′-deoxycytidine reorganization of pRB2/DNMT1 multimeric complex on ERα gene promoter and modulated its expression in breast cancer cell lines." (PMID 33604794, 2021). "The overexpression of DNMT1, a target of miR-148a/miR-152, was responsible for the hypermethylation of the miR-148a/miR-152 promoter and reduced expression of these two miRNAs in breast cancer cells." (PMID 34062726, 2021). "Epimutation by DNA Methyltransferase 1 (DNMT1), an epigenetic regulator enzyme, may lead to the proliferation of breast cancer." (PMID 33450856, 2021). "Therefore, developing drug candidates as DNMT1 inhibitors is a potential strategy for breast cancer treatment." (PMID 33450856, 2021). "Similarly, increased DNMT1 expression has been found in cancerous mammary gland tissues of a mammary cancer animal model." (PMID 33500531, 2021).
breast cancer (continued). "In addition, chromatin immunoprecipitation confirmed the binding of acetylated STAT3 to DNMT1 promoter as a consequence of increased p300 levels and subsequent interaction with DNMT1 in malignant T lymphocytes and breast cancer cell lines." (PMID 33604794, 2021). "In our present study, we found that DNMT1 expression increased in breast cancer tissues." (PMID 34150611, 2021). "DIM could enhance PTX sensitivity in MCF-7 and T47D breast cancer cells by reducing the expression of DNMT1 and subsequently reducing the methylation level of KLF4 and promoting the expression of KLF4." (PMID 34150611, 2021). "Highly expressed circ-DNMT1 binds and regulates oncogenic proteins in breast cancer cells." (PMID 33718157, 2021). "Meanwhile, MiR-1207-5p can target STAT6 to promote breast cancer growth, DNMT1 is a critical factor responsible for DNA methylation modification, VEGFA can trigger aberrant angiogenesis and induce immune evasion, and IGFBP5 is capable of regulating the insulin-like pathway." (PMID 34760687, 2021). "In addition, the downregulation of miR-152, which targets DNMT1 (an oncogene or cancer stemness marker), was observed in breast cancer cells." (PMID 34336125, 2021). "Furthermore, laccaic acid was found to inhibit DNMT1 activity and promote the reactivation of genes silenced by promoter methylation in breast cancer cell lines and in RGS6-/- mice." (PMID 32365701, 2020). "This supports our hypothesis that SOX2 directly transactivates DNMT1 expression and thereby alters the methylation landscape and feedback inhibits FOXO3a expression in breast cancer." (PMID 31296961, 2020). "Moreover, we demonstrated that SOX2 feedback inhibits FOXO3a expression by directly transactivating DNMT1, and inhibition of DNMT activity suppressed tumor growth via regulation of FOXO3a/FOXM1/SOX2 signaling in breast cancer." (PMID 31296961, 2020). "For instance, CUR inhibited DNMT1 activity in human breast cancer MCF-7 cell lines." (PMID 32962067, 2020). "Moreover, combined treatments with SFN and withaferin A promoted cell death in breast cancer cells through the inhibition of DNMT1, DNMT3a, and HDAC activities in MCF-7 cells." (PMID 30881375, 2019). "Interestingly, ISL1, as a direct DNMT1 target, hypermethylated and downregulated in mammary tumors and CSCs." (PMID 30674889, 2019). "We next assessed the possibility that ZC3H18 might affect E2F1 and DNMT1 differently in ovarian and breast cancer cells." (PMID 31604914, 2019). "Thus, for the first time, we demonstrate that OCT4 is dependent on ERα expression to suppress proliferation in ERα‐positive breast cancer cells through the regulation of DNMT1/ISL1 and the inactivation of ERK signalling pathway." (PMID 31012189, 2019). "In breast cancer cells, however DcR2 methylation was proposed to be solely mediated by DNMT1." (PMID 31248188, 2019). "Also, these compounds cause down-regulation of DNMT1, DNMT3a and DNMT3b in HCC1806 breast cancer cells." (PMID 30881375, 2019). "To explore the mechanism underlying SP3 knockdown-attenuated metastasis of MCF-7 and MDA-MB-231 cells, we attempted to confirm whether SP3 also impacted the expression of DNMT1 in breast cancer cells." (PMID 30386180, 2018). "The transcriptional link between BRCA1 and DNMT1 strongly indicates a function of BRCA1 in global DNA methylation, thus providing another plausible mechanism for BRCA1 mutation-associated DNA hypomethylation and breast cancer formation." (PMID 30558184, 2018).
breast cancer (continued). "Interestingly, it is likely that this combinatorial dietary regimen is more effective in regulation of DNMT1 expression in breast cancer MDA-MB-157 cells than MDA-MB-231 cells, which is opposite to what we have found in HDAC1 expression." (PMID 28839265, 2017). "For example, folic acid increased DNMT1 expression in breast cancer cell lines." (PMID 28422052, 2017). "In this study we aimed to investigate the impact of combinatorial SFN and WA on MCF-7 estrogen receptor-positive (ER (+)) and MDA-MB-231 ER (−) breast cancer cell proliferation in conjunction with their role in the epigenetic gene expression of DNMT1, DNMT3A, DNMT3B and HDAC1." (PMID 28534825, 2017). "Our present study demonstrates that ERα is an activator of DNMT1 and DNMT3b in breast cancer cells." (PMID 26980709, 2016). "Univariate analysis of the impact of epigenetic methylation-related protein expression on breast cancer patient prognosis showed that high expression of DNMT1 in malignant cells correlated with shorter OS (p = 0.041); however, the association was not significant in multivariate Cox analysis." (PMID 27071379, 2016). "As expected, reduction of DNMT1 expression by RNAi could partly reversed drug resistance phenotype of these two PTX-resistant breast cancer cell lines." (PMID 26980709, 2016). "Tumor expression of DNMT1 differed with breast cancer molecular subtype." (PMID 27071379, 2016). "Since the expression degree of DNMT1 differs by molecular and stromal subtypes, DNMT1 may very well be a new therapeutic target for breast cancer type with high DNMT1 expression." (PMID 27071379, 2016). "Then we addressed whether DNMT1 and DNMT3b were the downstream target genes of ERα in breast cancer drug resistance." (PMID 26980709, 2016). "We speculate that ERα-activated-DNMT1 pathway dominantly propels the drug-induced global DNA hypermethylation in breast cancer, although the effects of DNMT3a/3b cannot be fully excluded in this experimental system and remains to be tested further." (PMID 26980709, 2016). "The positive correlation between ERα and DNMT1 and DNMT3b expression suggested that ERα might be involved in up-regulation of the DNMTs in breast cancer drug response." (PMID 26980709, 2016). "The increased expression of DNMT1 and DNMT3b was, at least in part, a result of transcription up-regulation of these two genes, as the mRNA levels were correspondingly increased in these two drug resistant breast cancer cell lines." (PMID 26980709, 2016). "Elevated level of DNMT1 is observed in MCF-7 breast cancer cells." (PMID 25973397, 2015). "Previous studies demonstrated that ERα could upregulate Dnmt1 expression by directly binding to the DNMT1 promoter region in ER-positive human breast cancer cells MFC-7 cells." (PMID 26588706, 2015). "DNMT1 along with HDAC1 and (H3–K9) HMTase remain associated with the ER-α promoter, causing hypermethylation of 5′ CpG islands and thereby causes silencing of ER-α expression in breast cancer cells." (PMID 25973397, 2015). "Furthermore, two common catechol-containing coffee polyphenols such as caffeic acid and chlorogenic acid inhibits DNMT1 levels in breast cancer cells." (PMID 24822169, 2014). "Our study identified epigenetic-mediated DNMT1 transcriptional repression, which involved the hypermethylated E2F1 motif-mediated loss of active histone modification H3K9ac and transcription factor E2F1 enrichment in BRCA1-mutated breast cancer." (PMID 24502362, 2014). "A reduction in DNMT1 and DNMT3b was also shown in the mammary tumors in transgenic mice." (PMID 26161298, 2014). "In this study, we report for the first time that (i) BRCA1-mutated breast cancer displayed a hypermethylated E2F1 motif and promoter region; (ii) the hypermethylated E2F1 motif was negatively correlated with DNMT1 mRNA levels; and (iii) E2F1 is a key transcriptional regulator of DNMT1." (PMID 24502362, 2014).